RN7SL357P (RNA, 7SL, cytoplasmic 357, pseudogene)
Gene: Miscellaneous RNA gene on chromosome 4 (56,805,834 to 56,806,131, forward strand). Ensembl gene ENSG00000265894.
Homologues: Orthologues: chimpanzee Metazoa_SRP (99% identical), macaque Metazoa_SRP (94% identical). Paralogues in human: RN7SL1 (88% identical), RN7SL2 (88% identical), RN7SL3 (86% identical), RN7SL296P (85% identical), RN7SL126P (83% identical), RN7SL566P (83% identical), RN7SL786P (83% identical), Metazoa_SRP (82% identical), RN7SL492P (82% identical), RN7SL627P (82% identical), RN7SL732P (82% identical), RN7SL230P (82% identical), and 704 more.